LBX2 (ladybird homeobox 2)
Description:
Transcription factor.
Synonyms: LP3727
Tractability: No criterion of Open Targets' tractability assessment is met for any kind of drug.
Gene: Protein-coding gene on chromosome 2 (74,497,517 to 74,503,316, reverse strand). Ensembl gene ENSG00000179528.
Subcellular location: Nucleus
Subcellular location (Human Protein Atlas): Nucleoplasm; Midbody
Gene Ontology:
Molecular function: sequence-specific double-stranded DNA binding; DNA-binding transcription factor activity, RNA polymerase II-specific; DNA binding
Biological process: muscle cell differentiation; positive regulation of convergent extension involved in gastrulation; positive regulation of non-canonical Wnt signaling pathway; regulation of transcription by RNA polymerase II
Cellular component: chromatin; nucleus
Genetic constraint (gnomAD): Loss-of-function variants: 6 observed, 6.21 expected, observed/expected ratio (o/e) 0.97, 90% interval 0.52 to 1.75. That is too few expected variants to judge how well the gene tolerates losing a copy. Missense variants: 236 observed, 247.87 expected, observed/expected ratio (o/e) 0.95, 90% interval 0.86 to 1.06. Synonymous variants: 118 observed, 119.9 expected, observed/expected ratio (o/e) 0.98, 90% interval 0.85 to 1.15.
Homologues: Orthologues: chimpanzee LBX2 (98% identical), macaque LBX2 (94% identical), pig LBX2 (84% identical), rabbit LBX2 (84% identical), guinea pig LBX2 (77% identical), dog LBX2 (77% identical), mouse Lbx2 (77% identical), rat Lbx2 (76% identical), zebrafish lbx1a (53% identical), zebrafish lbx2 (51% identical), zebrafish lbx1b (48% identical), Drosophila melanogaster lbe (39% identical), and 1 more. Paralogues in human: LBX1 (53% identical).
Diseases named in the same sentence as LBX2 in open-access papers:
LBX2 is named in the same sentence as 9 diseases in open-access papers, as found by Europe PMC text mining. Sharing a sentence is not in itself a finding about the gene and the disease. The quoted sentences say what the papers report.
colorectal cancer (3 papers, 2022 to 2025). A primary or metastatic malignant neoplasm that affects the colon or rectum. "LBX2 was correlated with advanced tumor stage (III or IV), vascular invasion, and lymphatic invasion in colorectal cancer." (PMID 35795065, 2022).
lung adenocarcinoma (2 papers, 2020 to 2024). A carcinoma that arises from the lung and is characterized by the presence of malignant glandular epithelial cells. "LBX2 contributed to lung adenocarcinoma (LUAD) cell proliferation, migration, and invasion through the induction of EMT progression, indicating an oncogene role in the LUAD in vitro." (PMID 38520216, 2024).
glioma (1 paper, 2022). A benign or malignant brain and spinal cord tumor that arises from glial cells (astrocytes, oligodendrocytes, ependymal cells). "LBX2.AS1 has been reported to sponge miR-491-5p to further upregulate LIF and modulate the progression of glioma." (PMID 36033510, 2022).
scoliosis (1 paper, 2016). A congenital or acquired spinal deformity characterized by lateral curvature of the spine. "Unlike overexpression of lbx genes, lbx1b-/- and lbx2-/- mutant larvae displayed a straight trunk comparable to wild-type larvae, suggesting the involvement of gain-of-function but not loss-of-function of lbx1b in the body curvature phenotype that might be related to scoliosis susceptibility." (PMID 26820155, 2016). "Our lbx1b or lbx2 single knockout zebrafish mutants generated by targeting the first exon using Platinum TALENs also did not exhibit embryonic axial body curvature or scoliosis." (PMID 26820155, 2016).
tumor (9 papers, 2020 to 2025). "To validate our findings, we employed Kaplan-Meier survival curves and ROC curves to analyze the key genes associated with C2 tumor cell subtypes, including the top five transcription factors (IGF2, PRRX1, MAFB, LBX2, GATA2, MAFG)." (PMID 39896800, 2024). "Ladybird homeobox 2 (LBX2) is highly expressed in various tumors and is functionally linked to the regulation of essential tumor-related biological processes, such as cell proliferation and apoptosis." (PMID 37834260, 2023). "LBX2 was also superior to clinicopathological indicators including the depth of tumor invasion and lymphatic invasion with an AUC of 0.61and 0.63 respectively." (PMID 36313642, 2022). "LBX2 also had stable discriminative efficacy in different groups including age, sex, tumor size, depth of tumor invasion and clinicopathological feature." (PMID 36313642, 2022). "Taken together, these data indicate that LBX2 promotes LUAD tumor growth and metastatic activity in vivo." (PMID 32567804, 2020). "LBX2 also could identify LNM of CRC in tumor diameter less than 5cm and tumor diameter more than 5cm (P < 0.001)." (PMID 36313642, 2022). "We found that LBX2 silencing could inhibit subcutaneous tumor growth (volume and weight) and reduce visible organic metastatic lesions (in quantity) in vivo." (PMID 32567804, 2020). "Xenograft tumor models were used to assess the oncogenic role of LBX2 in vivo." (PMID 32567804, 2020). "Overall, our data suggest that LBX2 might participate in tumor proliferation, migration, and invasion through EMT progression." (PMID 32567804, 2020). "LBX2 protein levels in the tumor xenografts were verified by IHC." (PMID 32567804, 2020). "A recent study showed that LBX2 is expressed in various types of cancers and might be involved in tumor development." (PMID 32567804, 2020). "in vivo experiments showed that LBX2 overexpression increased tumor growth and metastasis." (PMID 32567804, 2020). "Moreover, overexpression of LBX2 evidently promoted tumor proliferation and metastatic activity in vivo." (PMID 32567804, 2020). "For example, it has been demonstrated that one of these lncRNAs (chr2:74,726,194–74,726,301), which is most relevant to host gene expression, could upregulate LBX2 expression via enhanced mRNA stability, and the overexpression of LBX2 correlates with tumor progression and poor prognosis in cancer." (PMID 39126025, 2024). "LBX2 serves carcinogenic functions in LUAD and is involved in tumor migration, proliferation, and invasion throughout EMT processes." (PMID 36349315, 2022). "Knockdown of LBX2 inhibited cell proliferation, migration and invasion of LUAD, whereas ectopic expression of LBX2 enhanced tumor growth, migration, and invasion." (PMID 32567804, 2020). "LBX2 is upregulated in CRC patients, and its overexpression promotes tumor growth." (PMID 36465397, 2022). "The current study suggests that LBX2 plays an oncogenic role in LUAD and may participate in tumor proliferation, migration, and invasion through EMT progression." (PMID 32567804, 2020).
cancer (3 papers, 2020 to 2025). A tumor composed of atypical neoplastic, often pleomorphic cells that invade other tissues. "Differentially methylated CpGs related to NXPH4 and LBX2 have previously been described in a study that developed a placental epigenetic clock, whereas aberrant methylation and/or expression of NXPH4, EPS8L2, AMOTL1, IRX2, and LBX2 have also been described in multiple types of cancers." (PMID 40338255, 2025).
LBX2 also shares sentences with these, for which no sentence is quoted: adenoma (1 paper); ependymoma (1); ovarian carcinoma (1).